PAX7 (paired box 7)
Diseases named in the same sentence as PAX7 in open-access papers (continued):
Sharing a sentence is not in itself a finding about the gene and the disease.
breast cancer (8 papers, 2019 to 2026). A primary or metastatic malignant neoplasm involving the breast. "Subsequent investigations should thoroughly investigate the biological mechanisms underlying PAX7 while also enhancing its potential applications in the personalized treatment of breast cancer." (PMID 41532150, 2026). "This disparity has indeed been pronounced, therefore underlining the potential of PAX7 as a biomarker in breast cancer." (PMID 41532150, 2026). "Through GSEA analysis, PAX7 was associated with breast cancer‐related signalling pathways and WNT signalling pathways." (PMID 40370330, 2025). "Elevated levels of PAX7 in breast cancer patients were linked to lower overall survival rates, while no notable prognostic correlation was found in glioma, lung adenocarcinoma, lung squamous cell carcinoma, or gastric adenocarcinoma." (PMID 40370330, 2025). "Prognostic analysis revealed that while PAX7 expression is associated with seven types of cancer, its prognostic significance is most pronounced in breast cancer." (PMID 40370330, 2025). "While PAX7 (Paired Box 7), a regulatory protein linked to muscle growth, has been connected to various cancers, its role in breast cancer is not well understood." (PMID 40370330, 2025). "PAX7 was specifically linked to the outcome of breast cancer, which is intriguing." (PMID 40370330, 2025). "Results showed high PAX7 expression in breast cancer linked to lower survival rates." (PMID 40370330, 2025). "In our study, we conducted an analysis of the survival of breast cancer patients based on the expression of PAX7, revealing that elevated levels of PAX7 were linked to unfavourable outcomes in terms of disease‐specific survival (DSS) and progression‐free interval (PFI)." (PMID 40370330, 2025). "Therefore, PAX7 may be a promising biomarker and potential therapeutic target in breast cancer, where high expression is associated with poor prognosis." (PMID 40370330, 2025). "Our current study demonstrate that genes involved in myogenesis (i.e., Pax7 and Myod) and muscle function (i.e., Myh1 and Pdk4), as well as miR-486, a regulator of myogenesis, are uniquely dysregulated in skeletal muscles based on breast cancer subtype and mutation pattern." (PMID 38651826, 2024). "PAX7 expression emerged as an independent prognostic factor for OS in breast cancer patients (HR = 1.459, 95% CI [1.027–2.072], p = 0.035)." (PMID 41532150, 2026). "Immunohistochemical staining results indicated that PAX7 staining intensity was greater in breast cancer tissues compared to normal tissues." (PMID 41532150, 2026). "This study systematically explored the expression and significance of the PAX7 gene in breast cancer by integrating public database resources and employing a series of bioinformatics analysis methodologies." (PMID 41532150, 2026). "The main aim is the establishment of the potential of PAX7 as a biomarker that will be highly useful for early diagnosis and targeted treatment with better clinical management and therapeutic strategy in breast cancer." (PMID 41532150, 2026). "Intriguingly, comparative analysis with other PAX family members (e.g., PAX3 and PAX9) revealed that PAX7 exhibits unique oncogenic specificity in breast cancer." (PMID 41532150, 2026). "To investigate the potential impact of PAX7 expression on patient survival, we utilized the GEPIA database to stratify breast cancer patients into groups exhibiting high and low PAX7 expression." (PMID 41532150, 2026). "In this investigation, we performed a comprehensive analysis of PAX7 expression patterns in breast cancer, revealing significant disparities compared to normal tissues." (PMID 41532150, 2026). "The data were categorized into two groups: 543 breast cancer patient samples exhibiting relatively low PAX7 expression and 544 samples with comparatively high PAX7 expression." (PMID 41532150, 2026). "The findings revealed that PAX7 expression in breast cancer tissues was markedly elevated compared to normal tissues." (PMID 41532150, 2026).
breast cancer (continued). "We examined the relationship between PAX7 expression and the extent of immune cell infiltration within the breast cancer microenvironment." (PMID 41532150, 2026). "This study will try to delve into how the PAX7 gene is expressed in breast cancer and its implications for the prognosis of the patients by analyzing various public databases." (PMID 41532150, 2026). "Subsequent studies should focus on resolving these concerns, examining the biological functions of PAX7, and assessing its clinical relevance for the development of personalized treatment strategies in breast cancer." (PMID 41532150, 2026). "With advanced statistical analysis, such as survival and Cox regression models, it will be explained how the PAX7 signature correlated with several clinical characteristics and overall survival (OS) in breast cancer patients." (PMID 41532150, 2026). "We evaluated the independent effects of PAX7 expression alongside other clinical characteristics on breast cancer prognosis employing the Cox proportional hazards model." (PMID 41532150, 2026). "Coupled with other well‐researched biomarkers such as HER2, ER, and PR, PAX7 can significantly enhance the specificity and accuracy of diagnosis in breast cancer." (PMID 41532150, 2026). "The model, along with the DEGs found in high‐throughput sequencing data and their enrichment in important biological processes, gave a thorough insight into the function of PAX7 in breast cancer." (PMID 40370330, 2025). "High PAX7 expression in breast cancer correlates with worse overall survival (OS), suggesting its potential as a prognostic biomarker." (PMID 40370330, 2025). "To investigate the correlation between PAX7 and the Wnt/β‐catenin signalling pathway in breast cancer cells, we employed the Wnt/β‐catenin signalling pathway‐specific activator SKL2001 for additional research." (PMID 40370330, 2025). "The calculated AUC was 0.678 (CI: 0.637–0.718), indicating that PAX7 is a promising biomarker for breast cancer." (PMID 40370330, 2025). "Our findings presented in this study highlight the significant role of PAX7 in various cancers, with a particular emphasis on its expression and prognostic value in breast cancer." (PMID 40370330, 2025). "Patients with high PAX7 levels in breast cancer had a significantly worse prognosis compared to those with low PAX7 levels, as indicated by the overall survival results (hazard ratio [HR] 1.46 (1.05–2.02); p = 0.023)." (PMID 40370330, 2025). "Further exploration of the role of PAX7 in breast cancer progression, particularly its regulation of the Wnt/β‐catenin pathway, is critical." (PMID 40370330, 2025). "The Kaplan–Meier analysis indicated a correlation between PAX7 levels and the prognosis of breast cancer." (PMID 40370330, 2025). "Experiments that reduced PAX7 expression in breast cancer cell lines (MDA‐MB‐468 and MDA‐MB‐231) revealed a significant influence on cell activity." (PMID 40370330, 2025). "Further studies are warranted to explore PAX7‐targeted therapies and their potential clinical applications in breast cancer treatment." (PMID 40370330, 2025). "We performed CCK‐8 assay and colony formation assay to evaluate the effect of PAX7 on the proliferation of breast cancer cells." (PMID 40370330, 2025). "Experiments involving Western blot, colony formation, and Transwell assays demonstrated that the suppression of PAX7 hindered the growth, infiltration, and movement of breast cancer cells by blocking the Wnt/β‐catenin pathway." (PMID 40370330, 2025). "Initially, we confirmed the presence of PAX7 in various typical breast cancer cell lines and observed that PAX7 expression is significantly elevated in MDA‐MB‐468 and MDA‐MB‐231 cell lines." (PMID 40370330, 2025). "This increase in Pax7 expression was also found in breast cancer-bearing mice as well as in other cancers pre-clinical studies, ultimately leading to muscle regeneration dysfunction." (PMID 34595171, 2021).
breast cancer (continued). "In the PyMT+ mammary tumor model, tumor-bearing mice contained lower skeletal muscle Pax7 as well as lower levels of MyoD along with the upregulation of circulating Tnf-α." (PMID 31941005, 2020). "This study concerns breast cancer, with a particular emphasis on the implications of the PAX7 gene." (PMID 41532150, 2026). "More importantly, the expression profile of PAX7 varies across different cancer types, further suggesting that its biological functions in breast cancer may be significantly specialized." (PMID 41532150, 2026). "In our gene expression analysis, differential expression assessments were done using the limma package in R, and indeed, the results showed that PAX7 expression is significantly greater in breast cancer tissues when compared to their normal tissue counterparts." (PMID 41532150, 2026). "Furthermore, Kaplan–Meier analysis leveraging the TCGA database was performed to elucidate the relationship between PAX7 expression and breast cancer prognosis." (PMID 41532150, 2026). "Indeed, it implies that PAX7 acts not only as a promising biomarker but also serves as an important determinant for estimating prognosis in patients with breast cancer." (PMID 41532150, 2026). "PAX7, as an autonomous prognostic factor, may influence the biological behavior of breast cancer cells and subsequently exert a considerable effect on patient prognosis by modulating various BPs including cell cycle progression and apoptosis pathways." (PMID 41532150, 2026). "Correlation between PAX7 expression and clinical characteristics of breast cancer." (PMID 41532150, 2026). "Therefore, a systematic investigation into expression patterns, biological functions, and relation to clinical features and prognosis would make available new information on PAX7 in the pathogenesis of breast cancer and support novel therapeutic strategies." (PMID 41532150, 2026). "Although PAX7 has been implicated in a wide range of cancers, its biological function and molecular mechanisms in breast cancer have not yet been fully understood." (PMID 41532150, 2026). "High levels of PAX7 in breast cancer were discovered to be associated with a negative prognosis after analysing clinical data from the TCGA database." (PMID 40370330, 2025). "The radar chart indicated a correlation between PAX7 levels and seven types of cancer, such as breast cancer (BRCA), glioma (GBM), lung adenocarcinoma (LUAD), lung squamous cell carcinoma (LUSC), gastric adenocarcinoma (STAD), prostate adenocarcinoma (PRAD), and thyroid cancer (THCA)." (PMID 40370330, 2025). "This study explores PAX7's significance in breast cancer and its mechanisms." (PMID 40370330, 2025). "PAX7 is expected to become a potential target for the treatment of breast cancer." (PMID 40370330, 2025). "PAX7 shows high expression levels in breast cancer (BRCA), lung adenocarcinoma (LUAD), lung squamous cell carcinoma (LUSC), gastric adenocarcinoma (STAD), and thyroid cancer (THCA), while also being highly expressed in prostate adenocarcinoma (PRAD) and glioma (GBM)." (PMID 40370330, 2025). "Nevertheless, there has been limited research on the involvement of PAX7 in breast cancer." (PMID 40370330, 2025). "This reciprocal feedback may also apply to breast cancer, where PAX7 can regulate components of the Wnt/β‐catenin pathway, such as β‐catenin, Wnt ligands, or inhibitors such as GSK3β, while modulating chromatin accessibility or recruiting coregulators." (PMID 40370330, 2025). "MDA‐MB‐468 and MDA‐MB‐231 breast cancer cell lines show significant expression of PAX7." (PMID 40370330, 2025). "Elevated levels of PAX7 in breast cancer are associated with a negative outlook, supported by clinical information from the TCGA repository." (PMID 40370330, 2025). "Further studies are needed to elucidate the role of PAX7 in breast cancer and its interaction with Wnt/β‐catenin signalling, which may underlie key processes such as proliferation, migration, and invasion." (PMID 40370330, 2025).
breast cancer (continued). "In particular, PAX7 showed elevated levels in breast cancer (BRCA), lung adenocarcinoma (LUAD), lung squamous cell carcinoma (LUSC), gastric adenocarcinoma (STAD), and thyroid cancer (THCA), with a decrease in expression observed in prostate adenocarcinoma (PRAD) and glioma (GBM)." (PMID 40370330, 2025). "The results of the study showed that inhibiting PAX7 could prevent the growth and invasion of breast cancer cells by blocking the Wnt/β‐catenin signalling pathway." (PMID 40370330, 2025). "Four potential breast-cancer-predisposing genes, i.e., UBASH3A, MYH13, UTP11L, and PAX7, were selected for further validation through transfection and ectopic expression of wild-type and mutated constructs followed by mass spectrometry profiling and/or Western blot analyses." (PMID 35625741, 2022). "Based on research into its molecular mechanisms, PAX7 may play a crucial role in the regulation of critical BPs involved in the proliferation, differentiation, and apoptosis of the breast cancer cells through precision regulation of the downstream gene cascades." (PMID 41532150, 2026). "This paracrine mechanism could create a permissive microenvironment for tumor progression, linking PAX7 overexpression to immune evasion.​ Cox regression analysis showed that PAX7 expression was an independent predictor of OS in breast cancer patients (HR = 1.459, 95% CI [1.027–2.072], p = 0.035)." (PMID 41532150, 2026). "Similarly, while in vitro experiments showed that PAX7 knockdown inhibited breast cancer cell proliferation, migration, and invasion, these experiments were performed in limited cell lines, and the heterogeneity of breast cancer requires validation across different molecular subtypes." (PMID 40370330, 2025). "In summary, because PAX7 greatly influences the outlook and is involved in important cellular functions controlled by the Wnt/β‐catenin signalling pathway, it could serve as a crucial biomarker and potential target for the treatment of breast cancer." (PMID 40370330, 2025). "Except for UTP11L and PAX7, these genes could be candidate genes for breast cancer." (PMID 35625741, 2022). "The mechanistic exploration revealed that PAX7 influences breast cancer through the Wnt/β‐catenin signalling pathway, resulting in reduced expression of β‐catenin, c‐MYC, and Cyclin D1 when PAX7 is suppressed." (PMID 40370330, 2025). "The expression levels of PAX7 in breast cancer tissues were significantly higher than normal tissues." (PMID 41532150, 2026). "The connection between PAX7 and negative outcomes is reinforced by examining disease‐specific survival (DSS) and progression‐free interval (PFI), especially within certain subcategories of breast cancer patients." (PMID 40370330, 2025).
sarcoma (8 papers, 2016 to 2024). A usually aggressive malignant neoplasm of the soft tissue or bone. "The effects of Pten deletion were dependent on PAX7 as Pax7 deletion rescued the phenotypes of Pten loss and altered tumor cell fate resulting in a spectrum of low-grade sarcomas with immunophenotypic smooth-muscle differentiation, including LMS." (PMID 34535684, 2021). "Altogether our data clearly indicate that perturbation of the SC niche microenvironment can give rise to distinct sarcoma subtypes in a Pax7 lineage-dependent manner, and provide evidence for a fibroblast cell origin of UPS." (PMID 26987019, 2016). "Thereby, we generated a cohort of MHI-null Pax7-null mice (herein referred as MHl-null P-null) sufficient to determine the effect of the Pax7 null background on sarcoma development." (PMID 26987019, 2016). "Altogether, our data demonstrate that selective perturbation of the SC niche results in distinct sarcoma subtypes in a Pax7 lineage-dependent manner, and define a critical role for the Met axis in sarcoma initiation." (PMID 26987019, 2016). "Genetic ablation of the muscle stem cells (obtained by moving the system in a Pax7 null background) strongly influenced the sarcoma subtype." (PMID 26987019, 2016). "The switch in sarcoma subtype is in line with the expansion of myofibroblasts observed in Pax7-null muscles upon exposure to a regenerative microenvironment." (PMID 26987019, 2016). "Altogether, our data show that perturbation of the SC niche with HGF can promote distinct sarcoma subtypes in a Pax7 lineage-dependent manner, thus offering a possible explanation of why ERMS and UPS are part of a tumor continuum." (PMID 26987019, 2016). "While FLI1 is unable to confirm EwS cases with FET–non-FLI1 translocations, NKX2-2 and PAX7 lack specificity and can be even strongly expressed in close morphological mimics such as EWSR1-NFATc2-positive sarcomas." (PMID 32164354, 2020). "Recently, PAX7 was identified as highly differentially expressed between ES and CIC rearranged sarcoma, also at the protein level." (PMID 32155762, 2020). "Molecular classification has been proposed, dividing RMS into two basic groups: fusion-positive RMS (either PAX7::FOXO1 enriched or PAX3::FOXO1 enriched) and fusion negative RMS (which is further sub-divided into well differentiated RMS, moderately differentiated RMS, and undifferentiated sarcomas)." (PMID 39020398, 2024).